KLHL8 (kelch like family member 8)
Description:
Substrate-specific adapter of a BCR (BTB-CUL3-RBX1) E3 ubiquitin ligase complex required for The BCR(KLHL8) ubiquitin ligase complex mediates ubiquitination and degradation of RAPSN.
Synonyms: KIAA1378
Tractability: Small molecule: it belongs to a druggable protein family. PROTAC: ubiquitination databases record sites on it.
Gene: Protein-coding gene on chromosome 4 (87,159,981 to 87,240,729, reverse strand). Ensembl gene ENSG00000145332.
Subcellular location (Human Protein Atlas): Nucleoplasm
Gene Ontology:
Molecular function: protein binding; ubiquitin-like ligase-substrate adaptor activity
Biological process: protein ubiquitination; ubiquitin-dependent protein catabolic process; proteasome-mediated ubiquitin-dependent protein catabolic process
Cellular component: Cul3-RING ubiquitin ligase complex; nucleoplasm; cytoplasm
Genetic constraint (gnomAD): Loss-of-function variants: 36 observed, 60.89 expected, observed/expected ratio (o/e) 0.59, 90% interval 0.45 to 0.78. The upper end of that interval is the gene's LOEUF score, 0.78, which puts it in group 3 of 6, group 1 being the genes least tolerant of losing a copy. Missense variants: 537 observed, 737.55 expected, observed/expected ratio (o/e) 0.73, 90% interval 0.68 to 0.78. Synonymous variants: 220 observed, 254.89 expected, observed/expected ratio (o/e) 0.86, 90% interval 0.77 to 0.96.
Homologues: Orthologues: chimpanzee KLHL8 (99% identical), macaque KLHL8 (99% identical), dog KLHL8 (98% identical), pig KLHL8 (97% identical), rabbit KLHL8 (96% identical), mouse Klhl8 (94% identical), guinea pig KLHL8 (94% identical), rat Klhl8 (93% identical), tropical clawed frog klhl8 (84% identical), zebrafish klhl8 (79% identical), Caenorhabditis elegans kel-8 (39% identical). Paralogues in human: KLHL20 (40% identical), KLHL1 (36% identical), KLHL5 (35% identical), KLHL17 (35% identical), KLHL3 (35% identical), KLHL4 (35% identical), KLHL2 (34% identical), KLHL12 (33% identical), KEAP1 (29% identical), KLHL18 (29% identical), KLHL28 (29% identical), IPP (28% identical), and 42 more.
Diseases named in the same sentence as KLHL8 in open-access papers:
KLHL8 is named in the same sentence as 5 diseases in open-access papers, as found by Europe PMC text mining. Sharing a sentence is not in itself a finding about the gene and the disease. The quoted sentences say what the papers report.
diabetes (1 paper, 2022). "Previous studies have shown that circ-KLHL8 could be used as a candidate biomarker for the diagnosis of diabetes and promote epithelial healing, regulating endothelial cell apoptosis, survival, and maintaining endothelial function through activating the miR-212-3p/SIRT5 signaling pathway." (PMID 35845080, 2022).
female infertility (1 paper, 2025). Diminished or absent ability of a female to achieve conception. "In this study, we focused on a KLHL member protein, KLHL8, that is highly expressed in mouse oocytes, and oocyte-specific deletion of Klhl8 caused MI arrest and female infertility, suggesting the essential role of KLHL8 in oocyte meiotic maturation." (PMID 40721554, 2025). "Oocyte-specific deletion of Klhl8 causes oocyte maturation defects and female infertility." (PMID 40721554, 2025).
schizophrenia (1 paper, 2024). A major psychotic disorder characterized by abnormalities in the perception or expression of reality. "While no prior studies have identified specific roles of PPM1L and KLHL8 in schizophrenia, our data nominate PPM1L and KLHL8 as potential regulators of MAP2 phosphorylation levels, and thus as novel targets for further exploration to reverse schizophrenia-related hyperphosphorylation of MAP2." (PMID 39532265, 2024). "Interestingly, novel gain-of-function interactions with PPM1L and KLHL8 nominated these as regulators of phosphoS1782 MAP2 abundance and potential therapeutic targets in schizophrenia." (PMID 39532265, 2024).
cancer (1 paper, 2014). A tumor composed of atypical neoplastic, often pleomorphic cells that invade other tissues. "In the cell morphology and connective tissue-associated cancer network, Ubc (ubiquitin C) is directly connected to all but three genes of interest (Bnipl, Gpr160, and Klhl8)." (PMID 25474466, 2014).
KLHL8 also shares sentences with these, for which no sentence is quoted: tumor (1 paper).